JMJD6 (jumonji domain containing 6, arginine demethylase and lysine hydroxylase)
Diseases named in the same sentence as JMJD6 in open-access papers (continued):
Sharing a sentence is not in itself a finding about the gene and the disease.
atherosclerosis (2 papers, 2022 to 2024). A disease characterized by the build-up of fatty material and calcium deposition in the arterial wall resulting in partial or complete occlusion of the arterial lumen. "The s-JMJD6-Ab levels were closely associated with some inflammation indicators, such as C-reactive protein and intima–media thickness (an atherosclerosis index)." (PMID 38732153, 2024). "This may be because JMJD6 can function in the progress of inflammation, and atherosclerosis accompanied by inflammation is a major cause of cerebral infarction." (PMID 38732153, 2024). "Importantly, higher levels of s-JMJD6-Abs were associated with certain inflammatory markers and correlated with atherosclerosis severity." (PMID 38732153, 2024). "This further supports the notion that s-JMJD6-Abs may predict the occurrence of atherosclerosis through their inflammatory effects, thus exhibiting higher levels in the sera of patients with cerebrovascular or cardiovascular diseases." (PMID 38732153, 2024). "This also suggests that s-JMJD6-Abs primarily reflect the progression of atherosclerosis, which may lead to the onset of ischemic stroke and AMI." (PMID 38732153, 2024). "Hence, JMJD6 may also contribute to the inflammatory process in atherosclerosis." (PMID 38732153, 2024). "Consequently, s-JMJD6-Abs may not simply manifest in all inflammatory contexts but may be indicative of specific inflammation-related diseases such as atherosclerosis and/or ischemic stroke." (PMID 38732153, 2024).
esophageal cancer (2 papers, 2023 to 2024). A primary or metastatic malignant neoplasm involving the esophagus. "An immunohistochemical analysis showed that JMJD6 was highly expressed in the inflamed mucosa of esophageal tissues, esophageal carcinoma tissues, and atherosclerotic plaques." (PMID 38732153, 2024). "Thus, we examined the expression of the JMJD6 protein in a surgically resected normal esophagus, the inflamed mucosa of the esophagus, esophageal carcinoma, and atherosclerotic plaques via immunohistochemistry." (PMID 38732153, 2024). "Our findings demonstrate high JMJD6 expression in inflamed esophagus tissue samples and esophageal carcinoma, but not in normal esophagus mucosa." (PMID 38732153, 2024).
gestational diabetes mellitus (2 papers, 2020 to 2021). "The abnormal expression of JMJD6 is closely related to neuropathic pain, gestational diabetes mellitus, and various tumorigenesis." (PMID 33500727, 2021). "Not surprisingly, abnormal expression of JMJD6 may contribute to the development of many diseases, such as neuropathic pain, foot‐and‐mouth disease, gestational diabetes mellitus, hepatitis C and various types of cancer." (PMID 31961032, 2020).
leukemia (2 papers, 2020 to 2026). A malignant (clonal) hematologic disorder, involving hematopoietic stem cells and characterized by the presence of primitive or atypical myeloid or lymphoid cells in the bone marrow and the blood. "Subsequent genome-wide association studies using these continuous risk scores uncovered novel disease-associated loci, including PPP1R15A for T2D and JMJD6/SRSF2 for leukemia, that were missed by traditional binary case definitions." (PMID 41627341, 2026). "To further characterize the role of Brd9&Jmjd6 and Kat6a&Jmjd6 in leukemia, we performed RNA-seq to compare the global transcriptional changes upon either single or double genetic perturbation of the targeted genes." (PMID 32661245, 2020). "This screen reveals synthetic sick interactions between Brd9&Jmjd6, Kat6a&Jmjd6, and Brpf1&Jmjd6 in leukemia cells." (PMID 32661245, 2020).
mesothelioma (2 papers, 2022 to 2023). A usually malignant and aggressive neoplasm of the mesothelium which is often associated with exposure to asbestos. "High levels of JMJD6 significantly reduced DFS in patients with KIRP, LUSC, and uveal melanoma (UVM), as well as OS in patients with KIRC and mesothelioma (MESO), suggesting the carcinogenic effect of JMJD6 in these tumors." (PMID 35359945, 2022).
metastatic disease (2 papers, 2017 to 2021). "Clinically, JMJD6 has been associated with more aggressive and metastatic disease, poorer prognosis, and lower overall survival rates—particularly in lung colon and oral cancers." (PMID 28587176, 2017).
metastatic melanoma (2 papers, 2017 to 2023). A melanoma that has spread from its primary site to another anatomic site. "Whereas the single use of anti-PD-1 antibody failed to induce significant antitumor effect in this study, JMJD6 knockdown overcame the resistance of metastatic melanoma cells to anti-PD-1 treatment, suggesting the combination potential of JMJD6 inhibition with ICB therapies." (PMID 37567973, 2023).
non-small cell lung carcinoma (2 papers, 2018 to 2021). A group of at least three distinct histological types of lung cancer, including non-small cell squamous cell carcinoma, adenocarcinoma, and large cell carcinoma. "Moreover, miR-770 inhibited tumorigenesis and EMT by targeting JMJD6 and regulating the WNT/β-catenin pathway in non-small cell lung cancer." (PMID 30524203, 2018).
oral cancer (2 papers, 2016 to 2017). "In addition several reports have shown that an overexpression of JMJD6 is associated with a poor prognosis in different cancers, in particular, in lung and oral cancer." (PMID 27556302, 2016). "These authors demonstrated that JMJD6 was positively correlated with oral carcinogenesis, was enriched in oral cancer stem cells (CSC), and was identified as a novel regulator of OSCCs." (PMID 27556302, 2016). "The recent identification of JMJD6–IL-4 axis as a novel regulator of oral CSCs is of particular interest given the plausibility that novel treatments targeting JMJD6 could be an effective treatment modality for oral cancer." (PMID 28587176, 2017).
uveal melanoma (2 papers, 2022). A melanoma derived from melanocytes of the uveal tract. "Besides, Ras-ERK1/2 signaling stimulates the malignant progression of uveal melanoma via the regulation of JMJD6-mediated H2A.XY39ph." (PMID 35359945, 2022). "For instance, MDM2 could regulate JMJD6 degradation to diminish H2A.X phosphorylation, thereby resulting in uncontrolled uveal melanoma cell migration." (PMID 35468881, 2022).
acute monocytic leukemia (1 paper, 2023). Acute monoblastic leukemia (AML-M5), is one of the most common subtypes of acute myeloid leukemia (AML) that is either comprised of more than 80% of monoblasts (AML-M5a) or 30-80% monoblasts with (pro)monocytic differentiation (AML-M5b). "An acute monocytic leukemia cell line, THP-1 was used to investigate the role of JMJD6 in human monocytes." (PMID 37567973, 2023).
adenoma (1 paper, 2020). A neoplasm arising from the epithelium. "Lesion-specific mutations in JMJD6, CNTNAP5 (adenoma-enriched), and GSG1L (carcinoma-enriched) were also identified." (PMID 32023847, 2020).
Alzheimer disease (1 paper, 2023). A progressive, neurodegenerative disease characterized by loss of function and death of nerve cells in several areas of the brain leading to loss of cognitive function such as memory and language. "A network analysis on deconvoluted bulk transcriptomic data from human Alzheimer’s disease cohorts identifies several potential key disease drivers, including JMJD6." (PMID 37188718, 2023).
Anophthalmia (1 paper, 2021). Absence of the globe or eyeball. "Knockout of Jmjd6 (Ptdsr) in mouse results in severe disruption in eye formation, with defects ranging from impaired retinal neuron differentiation to complete unilateral or bilateral anophthalmia." (PMID 33563331, 2021).
B-cell lymphoblastic leukemia (1 paper, 2025). "Although no translational clinical applications of either JMJD6 or PHF6 in DLBCL have been established to date, JMJD6 is involved in the maintenance and multilineage differentiation potential of HSCs, while the oncogenic effect of PHF6 is suggested in precursor B-cell lymphoblastic leukemia." (PMID 40282457, 2025).
cerebral infarction (1 paper, 2024). An ischemic condition of the brain, producing a persistent focal neurological deficit in the area of distribution of the cerebral arteries. "Therefore, s-JMJD6-Abs can be used to predict patients with cerebral infarction risk at the early stage." (PMID 38732153, 2024).
cerebrovascular diseases (1 paper, 2024). "Using AlphaLISA, we confirmed that s-JMJD6-Abs can serve as a potential biomarker for inflammation-related diseases including cerebrovascular diseases, cardiovascular diseases, DM, and cancers." (PMID 38732153, 2024).
cholangiocarcinoma (1 paper, 2023). A carcinoma that arises from the intrahepatic biliary tree (intrahepatic cholangiocarcinoma) or from the junction, or adjacent to the junction, of the right and left hepatic ducts (hilar cholangiocarcinoma). "We further reviewed the literature and found high JMJD6 expression was associated with improved OS and RFS in cholangiocarcinoma, which indicated that JMJD6 was one of the improved independent prognostic factors of OS and RFS." (PMID 37488513, 2023).
cutaneous melanoma (1 paper, 2018). A primary melanoma arising from atypical melanocytes in the skin. "Looking carefully into the skin cutaneous melanoma TCGA dataset we found that the levels of JMJD6 are upregulated in 16% of human cutaneous melanoma (72 out of 469 patients)." (PMID 30619488, 2018).
eyelid coloboma (1 paper, 2025). "This study reports the first case of a JMJD6 intronic pathogenic variant (c.941+75G > T) linked to congenital eyelid coloboma, expanding the known phenotypic spectrum of JMJD6 variants and their role in eyelid morphogenesis." (PMID 40034743, 2025). "In this study, we report the case of a patient with congenital eyelid coloboma caused by a JMJD6 pathogenic variant in one individual from a monozygotic twin pregnancy." (PMID 40034743, 2025). "We acknowledge that the association between the JMJD6 variant and eyelid coloboma is currently limited by the lack of functional validation." (PMID 40034743, 2025).
gallbladder cancer (1 paper, 2024). "The combined use of MST1R and JMJD6 inhibitors significantly enhances the anti-gallbladder cancer effect, potentially offering a viable combination therapy strategy for gallbladder cancer treatment." (PMID 39210450, 2024). "Furthermore, the concomitant utilization of MST1R and JMJD6 inhibitors manifested a synergistic anti-gallbladder cancer effect." (PMID 39210450, 2024). "It was observed that the Q values of MGCD-265 in combination with SKLB325, a JMJD6 inhibitor, were all greater than 1.15 for all three types of gallbladder cancer cells, suggesting that MGCD-265 in combination with SKLB325 might have a more potent anti-tumor effect." (PMID 39210450, 2024).
herpesvirus infections (1 paper, 2026). "Our findings unveil a novel epigenetic strategy employed by PRV to evade host antiviral responses and highlight JMJD6 as a potential therapeutic target for combating herpesvirus infections.IMPORTANCEThe ongoing conflict between viruses and host antiviral defenses is central to viral pathogenesis." (PMID 42053297, 2026).
Hypertension (1 paper, 2020). The presence of chronic increased pressure in the systemic arterial system. "Due to the increase of JMJD6 in hypoxic cell culture, we set out to determine if this protein was increased by chronic ischemia in vivo, by utilizing the rodent RUPP model of placental ischemia-induced hypertension." (PMID 32039444, 2020).
ischemic stroke (1 paper, 2024). A stroke disorder caused by obstruction of blood flow to the brain, due to thrombotic (local blood clot formation) or embolic (due to a blood clot or other material traveling from another site) event. "The levels of s-JMJD6-Abs showed a slight but significant elevation in patients with TIA/Asympt-CI and DSWMH, suggesting a potential association with the early stages of ischemic stroke." (PMID 38732153, 2024). "This study investigated the relationship between the levels of s-JMJD6-Abs and various inflammation-related diseases, including ischemic stroke, DM, AMI, and cancers." (PMID 38732153, 2024). "Elevated s-JMJD6-Ab levels were observed in patients with conditions such as ischemic stroke, AMI, DM, and various cancers, when compared to HDs." (PMID 38732153, 2024).
kidney cancer (1 paper, 2021). Primary or metastatic malignant neoplasm involving the kidney. "We used the Cancer Cell Line Encyclopedia (CCLE) dataset and observed that JMJD6 was highly expressed in kidney cancer relative to most other solid tumors." (PMID 33634984, 2021). "P300‐activated JMJD6 may constitute SEs to drive a series of kidney cancer‐related drivers, such as VEGFA, β‐catenin, or SRC." (PMID 33634984, 2021). "Particularly, high‐throughput sequencing data revealed that JMJD6 could assemble super‐enhancers to drive a list of identity genes in kidney cancer, including VEGFA, β‐catenin, and SRC." (PMID 33634984, 2021).
mental disorder (1 paper, 2022). A disease that has its basis in the disruption of mental process. "Eight genes are implicated in viral (SEC14L1, JMJD6, SRSF2, TMPRSS2, MX1, MX2) or bacterial (COL8A1, SPIRE1) infections, seven genes (MFSD11, METTL23, CTTNBP2, BACE2, IMPA2, MPPE1 and GNAL) are involved in mental disorders and one gene (MGAT5B) is related to the Golgi complex." (PMID 35581286, 2022).
mucinous ovarian cancer (1 paper, 2019). An invasive malignant neoplasm that arises from the ovary and is characterized by the presence of malignant epithelial cells that contain intracytoplasmic mucin and may resemble the epithelial cells of the endocervix or gastrointestinal tract. "JMJD6 was highly expressed in 31 (39.74%) of the 78 serous ovarian cancer patients and in eight (26.67%) of the 30 mucinous ovarian cancer patients." (PMID 31637004, 2019). "Kaplan–Meier survival analysis indicated that serous and mucinous ovarian cancer patients with high JMJD6 expression had a significantly shorter median overall survival as well as disease-free survival (p = 0.0002, p = 0.0087, p < 0.0001, and p < 0.0001, respectively)." (PMID 31637004, 2019).
osteoarthritis (1 paper, 2023). A noninflammatory degenerative joint disease occurring chiefly in older persons, characterized by degeneration of the articular cartilage, hypertrophy of bone at the margins and changes in the synovial membrane. "We therefore consider these approaches, including the study of osteoarthritis development in surgical and aging models, as the next steps in our quest to understand the role of NDRG2, WSB1, JMJD6, TSPYL2, HMGB2 and PPP1R15A in osteoarthritis and their inner mechanistic links." (PMID 37033917, 2023).
osteosarcoma (1 paper, 2022). A usually aggressive malignant bone-forming mesenchymal neoplasm, predominantly affecting adolescents and young adults. "As a regulator of the DNA damage epigenome, JMJD6 can be recruited to DNA double strand breaks (DSBs) during microradiation via downregulating H4K16ac, and ultimately modulates the DNA damage response in radiation-induced osteosarcoma cells." (PMID 35359945, 2022).
pancreatic cancer (1 paper, 2022). "Furthermore, the qPCR results indicated the mRNA expression levels of JMJD6, ANKZF1, CITED2, and ENO3 was obviously decreased in pancreatic cancer cells versus the normal pancreatic ductal epithelial cells, whereas those of LDHA, TES, and SIAH2 were oppisite." (PMID 35935823, 2022).
Stroke (1 paper, 2024). Sudden impairment of blood flow to a part of the brain due to occlusion or rupture of an artery to the brain. "In this study, we aimed to explore the potential role of serum anti-JMJD6 antibodies (s-JMJD6-Abs) in inflammatory-related diseases and to consider them as biomarkers for inflammatory myocardial infarction, stroke, DM, and cancers." (PMID 38732153, 2024). "Hence, JMJD6 autoantibodies may reflect inflammation, thereby serving as a potential biomarker for diagnosing specific inflammation-related diseases, including stroke, AMI, DM, and cancers, and for prediction of the prognosis in patients with EC." (PMID 38732153, 2024).
unstable angina pectoris (1 paper, 2024). "In particular, JMJD6 is an antigen recognized in serum IgG from patients with unstable angina pectoris (a cardiovascular disease)." (PMID 38732153, 2024). "In the present study, Jumonji C-domain-containing 6 (JMJD6) was identified through SEREX using serum from a patient with unstable angina pectoris (UAP), a cardiovascular disease." (PMID 38732153, 2024).